SMAD3 (SMAD family member 3)
Diseases named in the same sentence as SMAD3 in open-access papers (continued):
Sharing a sentence is not in itself a finding about the gene and the disease.
hepatocellular carcinoma (continued). "Collectively, the down-regulation of Smad3 expression at least partially contributed to the anti-proliferative effect of CDBEE in human hepatoma cells." (PMID 32477135, 2020). "In this study, we have demonstrated that CDBEE exhibited good anti-hepatoma activity in vitro and in vivo, which was partially mediated by downregulation of Smad3 expression." (PMID 32477135, 2020). "Using RNA interference, we demonstrated that CDBEE exerted anti-hepatoma activity partially through down-regulation of Smad3, one of major members in TGF-β/Smad signaling pathway." (PMID 32477135, 2020). "Based on the results of RNA-sequencing, the further investigation revealed that CDBEE inhibited Smad3 expression in human hepatoma cells and tumor tissues." (PMID 32477135, 2020). "Mechanistically, CDBEE inhibited Smad3 expression in human hepatoma cells and tumor tissues from nude mice." (PMID 32477135, 2020). "Genetically modified SMAD3-silenced human NK-92 cells inhibited cancer progression in two xenograft mouse models with human hepatoma and melanoma." (PMID 32161594, 2020). "Contrastingly, miR-92b-3p has also been reported to play an oncogenic role in the growth and invasion ability by regulating phosphatase and tensin homolog and Smad3 in bladder cancer, hepatocellular carcinoma, and glioblastoma cells." (PMID 29661250, 2018). "Activation of the AXL receptor is reported to aberrantly phosphorylate SMAD3 to induce EMT in hepatocellular carcinoma (HCC) progression in collaboration with TGF‐β." (PMID 28544151, 2017). "We made several novel predictions, including that CDK1 and PTPN1 knockdown would be more effective in males with hepatocellular carcinoma, and SMAD3 and HSPA4 knockdown would be more effective in females with head and neck squamous cell carcinoma." (PMID 26755347, 2016). "In conclusion, the results of the present study defined and supported a novel function for DHM, indicating that it induced cell apoptosis by downregulating ROS production via the TGF-β/Smad3 signaling pathway in mouse hepatocellular carcinoma Hepal-6 cells." (PMID 25376731, 2015). "Nagata showed that the inhibition of JNK switches Smad3 signaling from oncogenic pSmad3L/c-Myc to tumor-suppressive pSmad3C/p21WAF1 in DEN-induced rat hepatocellular carcinoma." (PMID 25714018, 2015). "It has been demonstrated that FHL3 physically and functionally interact with Smad2, Smad3, and Smad4, important regulators of cancer development and progression, and inhibit human hepatoma cell growth in vitro and in vivo." (PMID 24690879, 2014). "Akt when bound to Smad3 inhibits Smad3 phosphorylation and Smad3-induced apoptosis in hepatoma cells." (PMID 24759784, 2014). "Recently, it has been shown that FHL1, FHL2, and FHL3 physically and functionally interact with Smad2, Smad3, and Smad4, important regulators of cancer development and progression, and inhibit human hepatoma cell growth in vitro and in vivo." (PMID 24690879, 2014). "Nedd4 has been shown to participate in TGF-β signaling in hepatocellular carcinoma by regulating Smad3, though the detailed mechanism remains unclear." (PMID 41516261, 2025). "There is a member of the PAK family, P21-activated kinase 3 (PAK3), a serine or threonine protein kinase, that could achieve Epithelial–mesenchymal transition (EMT) of hepatocellular carcinoma by regulating Smad2 and Smad3." (PMID 37505298, 2024). "Moreover, autophagy triggered by starvation initiates EMT and invasion in hepatocellular carcinoma (HCC) cells through TGF-β/Smad3 signaling, and inhibition of autophagy by depleting Atg3 or Atg7 abolishes this effect." (PMID 38741166, 2024). "We discovered that overexpressed TAT could increase the expression of cleaved caspase-9, but knocking down Smad2 could decrease cleaved caspase-9 level in hepatoma cell lines, so as Smad3 and Smad4." (PMID 38769521, 2024).
hepatocellular carcinoma (continued). "Both drugs effectively decreased Smad6 expression and increased p‐Smad3‐Rho‐ROCK‐MLC signalling levels in HUVECs pre‐incubated with BMP9‐overexpressing HBV‐infected cells to a level similar to that in HUVECs pre‐incubated with HBV‐infected hepatoma cells." (PMID 37132170, 2023). "In addition, it has been shown that FOXP1 can affect the activation of the TGF-β pathway by binding to the transcription factors Smad2 and Smad3, thereby causing CD8+ T cells de-lymphotoxicity in hepatocellular carcinoma tissues." (PMID 37035153, 2023). "However, contrary to the CAFs-dependent pro-tumor properties, PPARγ reduces hepatoma cell metastasis by inhibiting the transcriptional activity of MMPs and smad family member 3 (SMAD3), thereby reducing hepatoma cell metastasis." (PMID 37251321, 2023). "In addition, starvation induced autophagy increases invasion and metastasis of hepatocellular carcinoma (HCC) via TGF-β/SMAD3 signaling." (PMID 34944772, 2021). "Furthermore, several studies reported that SMAD3 increases the adhesive ability of hepatocellular carcinoma (HCC) cells by the form of exosome, which promotes the lung metastasis." (PMID 33602253, 2021). "Intriguingly, suppression of TGF-β/Smad pathway by downregulating Smad3 may be partially responsible for the inhibition of proliferation and metastasis of human hepatoma cells induced by CDBEE." (PMID 32477135, 2020). "For example, miR-17 could play as an oncogene by downregulating SMAD3 expression in hepatocellular carcinoma." (PMID 32774166, 2020). "Moreover, decreased Smad3 contributed to the inhibition of proliferation, migration and invasion of human hepatoma cells exposed to CDBEE." (PMID 32477135, 2020). "Thus, anti-migration and -invasion effect of CDBEE was partially mediated by Smad3 in human hepatoma cells." (PMID 32477135, 2020). "In a study, it was observed that EVs of hepatocellular carcinoma (HCC) origin induced ROS in HCC cells through SMAD3 signaling and regulated CTC adhesion, thereby promoting metastasis." (PMID 38037077, 2023). "Exosomal circ-GSE1 promoteS immune escape of hepatocellular carcinoma (HCC) by inducing the expansion of regulatory T cells via the regulation of miR-324-5p/TGFBR1/Smad3/Tregs axis." (PMID 37525158, 2023). "For example, in colon cancer, Wnt5b-associated exosomes promote cancer cell migration and proliferation in a paracrine manner; hepatocellular carcinoma (HCC)-derived exosomes deliver SMAD3 protein and mRNA to detach HCC cells and facilitate their adhesion." (PMID 34205256, 2021). "Dysfunction of the TGF-β–regulated SPTBN1/SMAD3/CTCF complex increases stem cell–like properties in hepatocellular carcinoma (HCC) cells and enhances tumorigenesis in tumor-initiating cells in a mouse model." (PMID 33457451, 2020). "MicroRNAs 21 and 145 exhibit inverse expression in Hepatocellular carcinoma (HCC), but how they relate to Smad3 C-terminal and Link region phosphorylation (pSmad3C and pSmad3L) downstream of TGF-β/MAPK signaling, remains inconclusive." (PMID 29156696, 2017). "For example, in hepatocellular carcinoma cells, TGFβ1 upregulates MMP2 via Smad3, boosting invasiveness." (PMID 40646747, 2025). "In hepatocellular carcinoma, FOSL2 is a target gene of MiR-133a, which promotes the proliferation and metastasis of liver cancer cells through the TGF-β /Smad3 signaling pathway." (PMID 33712565, 2021). "In hepatocellular carcinoma cell lines, TRIB3 overexpression can increase the activity of TGFβ-SMAD3 by reducing the degradation of SMAD3 and promoting its translocation to the nucleus, which in turn promotes epithelial–mesenchymal transition." (PMID 33920424, 2021). "For instance, SMAD3 was indicated in the CRC of representative cell lines of DLBCL, colorectal cancer, pancreatic, hepatocellular carcinoma, breast, and gastric cancers." (PMID 35201514, 2021).
hepatocellular carcinoma (continued). "In human hepatocellular carcinoma cell lines (HCC), the HO-1/CO axis conferred resistance to the TGF-β growth inhibitory signal by increasing Smad3 phosphorylation at Thr-179 via the ERK1/2 pathway." (PMID 32699258, 2020). "Our previous data demonstrated that lncRNA DANCR, which was first identified in hepatocellular carcinoma (HCC), promoted the cell proliferation and chondrogenic differentiation through up-regulating the expression of Smad3 and STAT3." (PMID 28674107, 2017). "Recently, it was reported that Gas6-Axl signaling increases TGF-β1 expression in mesenchymal hepatocellular carcinoma (HCC) cells via the activation of c-Jun N-terminal kinase (JNK), which promotes Smad3 function." (PMID 27819283, 2016). "On the other hand, TGF-β inhibits GSK3β via ERK-MAPK in hepatocellular carcinoma and cultured peritoneal mesothelial cells, and GSK3 inhibition can lead to SMAD3 activation and fibrosis in cultured cardiac myocytes and fibroblasts." (PMID 26092126, 2015). "In addition, exosomal circGSE1 secreted by hepatocellular carcinoma cells (HCC) can induce the expansion of Treg cells by regulating the miR-324-5p/TGFBR1/Smad3 pathway, which promotes the secretion of immunosuppressive factors, inhibits the function of CD8+ T cells, and causes tumor immune escape." (PMID 38633106, 2024). "Additionally, PRMT1 is found to promote EMT through the TGF‐β1/Smad pathway in hepatic carcinoma cells, and is required for TGF‐β‐induced Smad3 activation, as well as promoting TGF‐β‐induced EMT." (PMID 37525933, 2023). "We found that JPHYD could inhibit the proliferation, invasion, and migration of hepatocellular carcinoma cells and JPHYD decreased the level of N-cadherin, Snail, Vimentin, Smad3, and Zeb1 and increased E-cadherin and Smad7 proteins." (PMID 35518787, 2022). "To further confirm the link between the SMAD3 signature and a mesenchymal state, we searched for similarities with other mesenchymal states identified in two other cancers (glioblastoma [GBM] and hepatoma)." (PMID 33724679, 2021). "MiR-133a could suppress hepatocellular carcinoma (HCC) by targeting Fos-related antigen 2 (FOSL2) and inactivating TGF-β/Smad3 signaling pathway." (PMID 33391416, 2021). "For example, a direct cross talk between Smad3 and STAT3 is bridged by p300 in hepatoma cells, a synergistic action of LIF-induced-Smad1 and BMP2-induced-STAT3 is bridged by p300 in neural cells, and Smad2/3 and STAT3 cooperatively interact in Th17 cell differentiation." (PMID 29963056, 2018). "Furthermore, another study found that SMAD3 blocked the phosphorylation of AKT, which promoted the chemosensitivity of hepatocellular carcinoma to cisplatin." (PMID 30594239, 2018). "In particular, the Hep3B, HepG2 and PLC hepatoma cell lines were found to have low TGF-β and Smad7 levels and strong Smad3 transcriptional activity and were thus sensitive to TGF-β cytostatic activity, representative of the early stages of chronic liver disease." (PMID 26013123, 2015). "Direct crosstalk between Smad3 and STAT3 was reported as the augmentation of IL-6-STAT3-mediated transactivation by TGF-β via interaction of the STAT3–pSmad3C complex bridged by p300 in hepatoma cells." (PMID 26194464, 2015). "In human hepatocellular carcinoma cells treated with TGF-β1 induction, reduced expression of the GnTIII gene and its catalytic product bisected GlcNAc structure, led to the up-regulation of Smad3 and Erk1/2 phosphorylation, which ultimately led to the EMT process of hepatocellular carcinoma." (PMID 38521909, 2024). "In hepatocellular carcinoma (HCC), ATF3 cooperates with SPTBN1 and SMAD3 to inhibit STAT3 activity, thereby suppresses HCC development." (PMID 30455690, 2018). "In addition, the Snail-Smad3/TGF-beta signaling pathway synergistically augments EMT and migration in hepatocellular carcinoma (HCC)." (PMID 38443979, 2024). "In human hepatocellular carcinoma (HCC), HepG2 cells can induce autophagy by EMT and TGF-β1/SMad3." (PMID 37666811, 2023).
hepatocellular carcinoma (continued). "When PAK3 was overexpressed in Huh7 and HepG2 hepatoma cells, the levels of p-Smad2 and p-Smad3 were significantly increased, while the levels of total Smad2 and Smad3 were almost unchanged, suggesting that PAK3 may act through the Smad-dependent TGF-β pathway to promote EMT in hepatoma cells." (PMID 34976179, 2022). "A previous study reported that Smad3, not Smad2, was the key mediator of TGF-β1-induced apoptosis in Hep3B hepatoma cells." (PMID 31189885, 2019).
Myocardial fibrosis (79 papers, 2012 to 2026). "But SMAD3 deficiency reduced 60% of pressure overload-induced myocardial fibrosis while significantly exaggerating cardiac hypertrophy." (PMID 36743695, 2023). "The amelioration of cardiac function and myocardial fibrosis was associated with an activation of silence information regulator 1 (Sirt1) which can directly combine with Smad3 and promote its deacetylation." (PMID 35081907, 2022). "Several researchers have reported that activation of Smad3 is associated with cardiac dysfunction, myocardial fibrosis, and cardiomyocyte apoptosis." (PMID 35330385, 2022). "We further determined the protective role of Smad3 deficiency in diabetic myocardiopathy by examining myocardial fibrosis, an indicator of chronic heart disease." (PMID 33733577, 2021). "Smad3 is one of the major downstream regulators that are associated with TGF-β1-mediated myocardial fibrosis." (PMID 33535854, 2021). "In order to illustrate the underlying molecular mechanisms of how RUNX1 regulates myocardial fibrosis, we examined whether the canonical Smad3-dependent TGF-β signaling could be activated by RUNX1 through luciferase reporter assay." (PMID 37927796, 2023). "In addition, Smad3 is pathogenic in cardiovascular diseases, and its overexpression could lead to myocardial inflammation, myocardial fibrosis, and insulin synthesis and secretion disorders, which is a key mediator in the pathogenesis of DCM." (PMID 39021834, 2024). "Collectively, our findings reveal BMAL1 as a critical negative regulator of post-MI myocardial fibrosis by inhibiting the TGF-β1/SMAD3 pathway mediated by SMAD7." (PMID 41909150, 2026). "QL inhibits the TGF-β1/Smad3 signaling pathway through up-regulation of miR-133a and miR-345-3p, thereby attenuating myocardial fibrosis and improving cardiac function." (PMID 40881586, 2025). "In summary, the mechanism of QL treat of myocardial fibrosis is mainly related to the down-regulation of TGF-β1/Smad3, in which inflammatory mediators like NLRP3, miR-133a and miR-345-3p play an important role." (PMID 40881586, 2025). "S100a9hi macrophages can stimulate fibroblasts to differentiate into myofibroblasts via the TGF-β/p-Smad3 signalling pathway, promoting myocardial fibrosis through MMT." (PMID 39445007, 2024). "Due to the abnormal activation of USP7, SMAD3 was upregulated, which in turn increased the EndMT process of ECs, promoted myocardial fibrosis, and accelerated the progression of HFpEF." (PMID 39346543, 2024). "By regulating the TGF-β1/Smad3 pathway, ginsenoside alleviates isoproterenol-induced myocardial fibrosis and heart failure." (PMID 39141645, 2024). "In myocardial infarction studies, activation of Smad2 and Smad3 led to myocardial fibrosis and cardiac remodeling." (PMID 36878974, 2023). "Increased expressions of SMAD2 and SMAD3 contributed to myocardial fibrosis in patients with HOCM, which happened early in childhood and continued through adulthood." (PMID 36878974, 2023). "The ability of ISO to cause myocardial fibrosis in rats was demonstrated by the increased TGF-β, collagen III, and phosphorylated Smad2/Smad3 protein levels." (PMID 36964489, 2023). "ES combined with radiotherapy aggravated myocardial fibrosis after radiation through TGF-β1/Smad3/CTGF signaling pathway." (PMID 35279096, 2022). "Rresveratrol effectively ameliorated myocardial fibrosis and improved cardiac function by regulating Sirt1/Smad3 deacetylation pathway in the rat model with dilated cardiomyopathy." (PMID 35081907, 2022). "Increased plasma Gal-3 concentration promotes myocardial fibrosis by activating the TGF-β/Smad3 signaling pathway, leading to cardiac remodeling and LA dilation." (PMID 36057558, 2022). "Myocardial fibrosis is associated with up-regulation of TGF-β1 and the downstream Smad2 and Smad3 proteins, as well as down-regulation of Smad7 expression." (PMID 35279096, 2022).